WASH4P (WASP family homolog 4, pseudogene)
Description:
May act as a nucleation-promoting factor at the surface of endosomes, where it recruits and activates the Arp2/3 complex to induce actin polymerization, playing a key role in the fission of tubules that serve as transport intermediates during endosome sorting.
Synonyms: FLJ31670; formerly FAM39CP
Gene: Transcribed unprocessed pseudogene on chromosome 16 (14,381 to 18,068, reverse strand). Ensembl gene ENSG00000234769.
Subcellular location: Early endosome membrane; Recycling endosome membrane